CXCL10 (C-X-C motif chemokine ligand 10)
Diseases named in the same sentence as CXCL10 in open-access papers (continued):
Sharing a sentence is not in itself a finding about the gene and the disease.
ovarian carcinoma (76 papers, 2010 to 2026). A malignant neoplasm originating from the surface ovarian epithelium. "The presence of CXCL10+ M1-type TAMs is associated with better clinical outcomes, greater chemotherapy response, and improved survival in ovarian cancer patients." (PMID 40330466, 2025). "The study also observed a prominent inverse association between CCL23 and CXCL10 levels in ovarian cancer patient samples that correlated with patient survival." (PMID 41463176, 2025). "Recently we discovered that CXCL10 can be processed to an inactive form in ovarian cancers and that its measurement has diagnostic significance." (PMID 37958440, 2023). "As a result of increased infiltration of effector cells, elevated CXCL10 expression has been associated with patient survival in ovarian cancer." (PMID 38035101, 2023). "It is often released by cancer cells undergoing T cell attack, and the expression of CXCL10 was found to be associated with better prognosis in ovarian cancer." (PMID 37348499, 2023). "With the help of several computational algorithms, we quantified the population-specific TME cell infiltration and TME signatures based on relevant gene sets, both of which were significantly associated with CXCL10-related risk in ovarian cancer." (PMID 34386037, 2021). "To better clarify the functionality of the TME signature of CXCL10-mediated risk in ovarian cancer, we tested known TME signatures in four independent cohorts." (PMID 34386037, 2021). "In this large-scale multi-platform study of 10 microarray datasets consisting of 1,673 ovarian cancer patients, we comprehensively evaluated CXCL10 and CXCL9 expression risk classifications for predicting overall survival (OS) and TME immune characteristics." (PMID 34386037, 2021). "Therefore, we generated four independent cohorts that covered the most common microarray platforms, ultimately elucidating the comprehensive landscape of CXCL10 in ovarian cancer clinical outcomes, TME characteristics, and underlying mechanisms." (PMID 34386037, 2021). "High expression of CXCL10 in ovarian cancer has been associated with improved overall survival." (PMID 34944392, 2021). "Finally, a linear correlation of dipeptidyl peptidase 4 (DPP4) and CXCL10 expression was observed in ovarian cancer patients, suggesting a regulatory association between chemokine substrate and the protease DPP4." (PMID 31482487, 2019). "Thus, in contrast to its favourable prognostic role in other cancer entities and in contrast to the positive prognostic impact of other T-cell and NK cell recruiting chemokines (e.g. CXCL9 and CXCL10) in ovarian cancer, elevated CX3CL1 levels are associated with worsened outcome in HGSOC." (PMID 39862711, 2025). "However, increased CXCL10 abundance has also been correlated with enhanced lymph node metastasis in other models, whilst decreased concentrations of CXCL10 in plasma have been associated with improved progression-free and overall survival for ovarian cancer patients." (PMID 34200333, 2021). "High levels of CXCL10+ TAMs have been correlated with improved chemotherapy response and overall survival in ovarian cancer patients, particularly in HGSOC." (PMID 40330466, 2025). "Such an understanding of the crosstalk between CCL23, STAT3, and CXCL10 provides new insights into future therapeutic targets and improving the responsiveness of ovarian cancers to current immune-oncology therapies." (PMID 41463176, 2025). "This highlights the need for subtype-specific investigations before generalizing the role of CXCL10 across all ovarian cancer cases." (PMID 40330466, 2025). "Although the deletion of IL15 and CXCL10 was consistently observed in independent cohorts of ovarian cancer and lung cancer patients, the direct functional implication of these two genes on TLS formation requires further investigation in future studies." (PMID 37348499, 2023).
ovarian carcinoma (continued). "In ovarian cancer, CXCL10+IRF1+STAT1+ M1 resulted in improved antigen processing capacity and T-cell infiltration, as well as a better patient prognosis." (PMID 38035101, 2023). "A large number of cytokines have been reported as elevated in ovarian cancer ascites samples including IL-6, IL-8, IL-10, IL-15, IP-10/CXCL10, MCP-1/CCL2, Mip1α/CCL3, Mip1β/CCL4, MDC, and VEGF." (PMID 36860657, 2023). "In preclinical models of ovarian cancer, increased expression of CXCL10 can reduce tumor burden and ascites accumulation." (PMID 35131874, 2022). "In vivo experiments showed that compound 968 increased the infiltration of CD3+ T cells into ovarian cancer and enhanced the secretion of CXCL10 and CXCL11 by ovarian cancer cells." (PMID 36523985, 2022). "In the context of the contribution of HRD in ovarian cancer, CXCL10 provides a neoteric perspective on markers of immunotherapy." (PMID 36704336, 2022). "Increased levels of the chemokines CXCL9, CXCL10, CXCL11, and CCL5 are all associated with an immune-reactive ovarian cancer microenvironment and improved patient prognosis." (PMID 35131874, 2022). "CXCL10 expression is correlated with antigen processing and tumor-infiltrating lymphocyte (TIL) infiltration in ovarian cancer and positively associated with patient’s OS." (PMID 34386037, 2021). "In short, our data discovered the effects of different CXC chemokines on ovarian cancer and conducted in-depth verification of CXCL10 in two aspects: immune regulation and angiogenesis." (PMID 34794429, 2021). "In summary, we found that CXCL10 can inhibit the growth of ovarian cancer by increasing immune killing and inhibiting angiogenesis." (PMID 34794429, 2021). "Real-time quantitative PCR (qRT-PCR), immunoblotting, and ectopic tumor formation experiments were used to verify the effect of CXCL10 on ovarian cancer tumors." (PMID 34794429, 2021). "In this study, we carried out an analysis of 1,673 ovarian cancer patients from 10 valid studies and identified the expression patterns of CXCL10 and CXCL9 together with their related TME immune characteristics." (PMID 34386037, 2021). "In ovarian cancers, CXCL10 over-expression defines a subset of high-grade, serous ovarian cancer′s termed “immunoreactive”, highlighting its established functions in adaptive immunity." (PMID 34200333, 2021). "This study was the first to screen CXC chemokine markers in ovarian cancer through bioinformatics methods, and verified through in vivo and in vitro experiments that CXCL10 influences the process of ovarian cancer immune response and angiogenesis." (PMID 34794429, 2021). "In particular, in the omentum of ovarian cancer patients, high levels of CXCL-10 and CCR5 have been described." (PMID 34440886, 2021). "Estimation of CXCL10 risk pattern sheds a novel insight on ovarian cancer TME immune characteristics and provides strategies for ovarian cancer immunotherapy." (PMID 34386037, 2021). "In line with this, our results observed that CXCL10 played a prior role in ovarian cancer immune characteristics and progress when compared to CXCL9." (PMID 34386037, 2021). "Consistent with previous studies on genomic instability in ovarian cancer, we observed that CXCL10-related immune signature genomic alteration was obviously higher in the high-risk classification." (PMID 34386037, 2021). "In summary, our current study suggested the biological process and prognostic roles of CXCL10 in more than 1,000 cases of ovarian cancer." (PMID 34386037, 2021). "Whilst evidence suggests that CXCL10 plays an important role in tumour pathogenesis, its role in ovarian cancers has remained unclear." (PMID 34200333, 2021). "We therefore assessed CXCL10 detection in ascites fluid from ovarian cancer patients (n = 212) as a representative, complex biological matrix." (PMID 34200333, 2021).
ovarian carcinoma (continued). "Through the pROC package analysis, we observed that CXCL10 showed a predictive advantage in the infiltration group when compared to CXCL9 in four independent groups of ovarian cancer (left)." (PMID 34386037, 2021). "CXCL10 is abundant in ascites fluid from ovarian cancer patients, where it is involved in the CXCR3-mediated migration of cancer cells and specific T-cell subsets." (PMID 34200333, 2021). "Accumulating evidence indicated that CXCL10 plays a crucial role in ovarian cancer, such as regulating tumor progression, TIL infiltration, and associated gene expression." (PMID 34386037, 2021). "TGF-β secretion can promote ovarian cancer metastasis, which stimulates CAFs to secrete cytokines and chemokines, including IL-6, CXCL10, and CCL5, that favor cancer cell metabolism and energy production." (PMID 34440886, 2021). "CXCL10 was found to be a robust prognostic biomarker and verified to have a high predictive power for ovarian cancer TME immunological characteristics." (PMID 34386037, 2021). "To establish proof-of-principle for the use of ART to discriminate between benign vs malignant disease, we measured active vs total CXCL10 concentrations in ascitic fluid harvested from patients with either benign or malignant ovarian tumours." (PMID 34200333, 2021). "We previously identified that malignant ovarian tumour tissues contained cleaved CXCL10, which correlated with reduced T-cell infiltrate." (PMID 34200333, 2021). "For example, CXCL10 gene encodes an important chemokine to recruit CD8+ T cells and is also highly expressed in ovarian cancer cells." (PMID 31059559, 2019). "Its expression has been found to increase upon treatment with demethylating agents in ovarian cancer cells, suggesting that promoter methylation controls CXCL10 expression." (PMID 29666625, 2018). "In ovarian cancer, all of the up-regulated genes were increased with more advanced stage (CXCL10, RIPK2 and SPP1) or higher pathological grade (CXCL11, KPNA2, RSAD2, THOC4 and TNC)." (PMID 23536776, 2013). "CXCL10 is crucial in M1-polarized TAMs in ovarian cancer by promoting antitumor immunity." (PMID 40330466, 2025). "Targeting the macrophage population to reprogram or enhance TAMs into an M1-polarized, CXCL10-secreting state offers a promising new therapeutic approach, particularly for ovarian cancer subtypes like clear cell carcinoma (CCC), which are often marked by immune exclusion and poor prognosis." (PMID 40330466, 2025). "Therefore, CXCL10 in M1-polarized TAMs is a key factor in driving immune-mediated tumor suppression and enhancing therapeutic efficacy in ovarian cancer." (PMID 40330466, 2025). "Its function in ovarian cancer has been much less studied than that of CXCL9 or CXCL10." (PMID 39862711, 2025). "For instance, trimethylation at H3K27 represses the production of CXCL9 and CXCL10 in ovarian cancer, establishing an immune-suppressive TME, while DNMT1 is responsible for the decreased CXCL12 in osteosarcomas, resulting in reduced CTL recruitment at the cancer site." (PMID 39000359, 2024). "Promoted the production of blood vessels and inhibited CXCL9 and CXCL10 in ovarian cancer cells." (PMID 39906741, 2024). "The presence of DPP4-cleaved shortened CXCL10 in human high-grade ovarian cancer tissues suggests that the truncated form of CXCL10 may induce an immunosuppressive tumor microenvironment." (PMID 37218983, 2023). "Further development may present an opportunity to apply new biomarkers such as the CXCL10 active ratio in a future screening context for ovarian cancer." (PMID 37958440, 2023). "EOC patients showed higher levels of proinflammatory cytokines (IL-6, TNF-α, and IL-12), regulatory cytokines (IL-10), and chemokines (CXCL-9 and CXCL-10), which corroborated this environmental proinflammatory/regulatory mechanism for the development of ovarian cancer." (PMID 38141599, 2023).
ovarian carcinoma (continued). "Similarly, the methyltransferase inhibitor decitabine increases the Cxcl10 (and also other chemokines, such as Ccl5) expression by ovarian cancer cells." (PMID 36429101, 2022). "Further in vivo assay had shown that CXCL10 could affect the progression of ovarian cancer by increasing the expression of cytotoxic T cells and inhibiting angiogenesis." (PMID 34794429, 2021). "We revealed that CXCL10 expression tended to be positively associated with prognosis and play a prior role in TME immune characteristics in certain stages and most samples of ovarian cancer." (PMID 34386037, 2021). "Furthermore, we selected an animal model of ovarian cancer that overexpressed CXCL10 for verification." (PMID 34794429, 2021). "The study found that CXCL10 could inhibit tumor growth by constructing a model of ovarian cancer with overexpression of CXCL10." (PMID 34794429, 2021). "A recent study using mouse models of ovarian cancer has shown that the reduced production of CXCL9 and CXCL10 from cancer cells is caused by enhancer of zeste homolog 2 (EZH2) mediated histone modification and DNA methyltransferase 1 (DNMT1) mediated DNA methylation of the chemokine genes." (PMID 30483271, 2018). "The epigenetic regulation of CXCL10 in ovarian cancer suggests that treatment with a demethylating agent such as Decitabine (which is also known to induce type I IFN signaling) could aid in the induction of ICD." (PMID 29666625, 2018). "Also, ASCs have a high expression of CCR5 and release CXCL-10 in ovarian cancer." (PMID 40076892, 2025). "Furthermore, DPP4-typical cleavage products of CXCL10 were detected in human ovarian carcinoma." (PMID 40579444, 2025). "Thus, CXCL10 presented a prior role in ovarian cancer when compared to CXCL9." (PMID 34386037, 2021). "Both CXCL10 and CXCL11 mediate CD8+ T-cell responses, and CXCL10 promotes C8+ T-cell activation in ovarian cancer." (PMID 40689422, 2025). "The current study developed a predictive model of CSOARG for prognosis in ovarian cancer using eight key genes (WNK1, ANGPTL4, AREG, IGF1, CXCL10, GMPR, FANCB, LYG1)." (PMID 40510161, 2025). "High expression of CXCL2, CXCL10, and CXCL11 is correlated with favorable prognoses in ovarian cancer." (PMID 40689422, 2025). "A previous study reported that CSF1 blockade in ovarian cancer models resulted in a significant reduction in CD163+ M2-like TAMs, with a concomitant increase in M1-polarized macrophages producing CXCL10, a chemokine crucial for T-cell recruitment." (PMID 40330466, 2025). "Ovarian cancer chemokine landscape profiling revealed chemokines such as CCL2, CCL4, CCL5, CXCL10, and CXCL12 as potential candidates in ovarian cancer." (PMID 41424784, 2025). "In a cultured cell line derived from the ascites of a patient with platinum resistant ovarian cancer (ET2), elevated levels of CCL2, CCL3, CCL4, CCL5, CXCL1, CXCL8 and CXCL10 were detected in the cultured media." (PMID 41424784, 2025). "Univariate Cox analysis demonstrated that CXCL9, CXCL10, CXCL11, and CXCL13 were protective factors in ovarian cancer (HR < 1, p < 0.01)." (PMID 38054797, 2023). "Studies have shown that CDK4/6 inhibition combined with PD-1 blockade treatment has higher CXCL10 and CXCL13 levels and CD8 + and CD4 + T cell activity than monotherapy-treated ovarian cancer." (PMID 37005667, 2023). "A study indicates that EZH2 inhibits chemokines, such as CXCL9 and CXCL10, thus impairing the trafficking for CD8+ T cells in human ovarian carcinoma." (PMID 35911718, 2022). "It has also been reported that the expression of CXCL9, CXCL10, and CXCL11 is upregulated in the tumor tissues of patients with colon cancer, esophageal cancer, lung cancer, and ovarian cancer, and correlates with better clinical outcomes." (PMID 34885241, 2021). "The synergistic effect between CXCL10 and specific TME immune cells is one of the most important factors to prolong patient survival of ovarian cancer." (PMID 34386037, 2021).
ovarian carcinoma (continued). "Meanwhile, the chemokine landscape of ovarian cancer was found to be quite heterogeneous, because of different functions of known lymphocyte-recruiting chemokines in TME, such as CCL2, CXCL9, CXCL10, CXCL12, and CXCL16." (PMID 34386037, 2021). "The CXCL10 and CXCL9 expression levels showed a positive correlation in four independent groups of ovarian cancer." (PMID 34386037, 2021). "The transcriptional levels of CXCL1, CXCL8, CXCL10, CXCL11, CXCL12, CXCL13, and CXCL14 were significantly elevated while CXCL3 was obviously reduced in ovarian cancer vs normal ovarian tissue." (PMID 33763130, 2021). "In patients with ovarian cancer, IL-17 derived from Th17 cells has been shown to induce the production of CXCL9 and CXCL10 by tumor cells and tumor infiltrated macrophages, which recruits CXCR3-expressing CTLs and NK cells into tumor tissues." (PMID 34885241, 2021). "Recently, therapeutic modulators that induce CXCL10 and CXCL9 expression were reported to improve immune cell responses and TME in ovarian cancer." (PMID 34386037, 2021). "Combined with the results in ovarian cancer, we surmise that CXCL9 and CXCL10 exert tumor-suppressive function by TIL recruitment through the JAK/STAT and NF-κB pathways." (PMID 32963527, 2020). "Previous studies showed that BMPER, CXCL10, and HOXA9 promote tumor angiogenesis and tumorigenesis in lung cancer, colon cancer, basal cell carcinoma, ovarian cancer, and liver tumor." (PMID 32432046, 2020). "For instance, T cell-recruiting chemokines CXCL9, CXCL10, and CXCL11 are favorable prognostic indicators in ovarian cancer, but are unfavorable indicators for pancreatic and renal cancer." (PMID 30873179, 2019). "In human ovarian cancer, the existence of DPP4-mediated CXCL10 cleavage products was demonstrated, suggesting a relevant role for these mechanisms also in patients." (PMID 31482487, 2019). "As the metastatic tumor grows and depletes the adipocytes in the omentum, the IL-6, CXCL10, and CCL5 secreted by the CAFs induce the ovarian cancer cells to start utilizing glycogen." (PMID 30380628, 2018). "In contrast, in ovarian cancer, high CXCL9 and CXCL10 expression doubled the overall survival time due to improved recruitment of tumor-infiltrating lymphocytes." (PMID 30319622, 2018). "Early studies have also reported enrichment of pro-inflammatory cytokines such as IL-6, CXCL10, and CD54 in ascites and have a pro-metastatic role in ovarian cancer progression." (PMID 27825119, 2016). "In the current study, we performed a comparative analysis on mRNA expression of CXCR3, CXCL-10 (IP-10), CXCR4, CXCL-12 (SDF-1α), IL-4 (interleukine-4) and IL-10 in tissues of benign and malignant ovarian tumors by the qRT-PCR method." (PMID 25999622, 2015). "We compared the mRNA expression of CXCR3, CXCL-10, CXCR4, CXCL-12, IL-4, and IL-10 in tissues of benign and malignant ovarian tumors by qRT-PCR method and evaluated serum IL-10 and CA-125 content of these patients by ELISA during one year." (PMID 25999622, 2015). "In contrast, ovarian cancer subtypes lacking CXCL10+ TAMs, such as clear cell carcinoma (CCC), exhibit poorer immune infiltration and worse prognoses." (PMID 40330466, 2025). "However, IL-17 has also been demonstrated to induce the secretion of CXCL9 and CXCL10, which in turn recruited effector CTL and NK cells to inhibit ovarian cancer." (PMID 39906741, 2024). "Thus, we also examined CXCL9, CXCL10, CXCL11 in the ovarian cancer cell lines, ES2 and SKOV3, that overexpress ISG20, and found that CXCL10 and CXCL11 were significantly upregulated." (PMID 37342328, 2023). "We identified that evaluation of CXCL10 expression could predict the tumor development, immune cell infiltration, TME signature, genetic alteration, and patient prognosis in ovarian cancer." (PMID 34386037, 2021).